DOCK4 (dedicator of cytokinesis 4)
Diseases named in the same sentence as DOCK4 in open-access papers (continued):
Sharing a sentence is not in itself a finding about the gene and the disease.
dyslexia (9 papers, 2010 to 2025). A learning disorder characterized by an impairment in processing written words. "Of note, the father of individual 2, who transmitted one variant in DOCK4, has a bipolar disorder, attention deficit hyperactivity disorder, anxiety and dyslexia." (PMID 38526744, 2024). "The current study focuses on two DOCK4 variants, Exon27-52 deletion (protein product: Dock4-945VS and rs2074130 variation (protein product: Dock4-R853H), which are associated with dyslexia and/or ASD with reading difficulties." (PMID 32009906, 2019). "DOCK4 variations associated with autism spectrum disorder and Dyslexia." (PMID 32009906, 2019). "Two DOCK4 variations, Exon27-52 deletion (protein product: Dock4-945VS) and a missense mutation at rs2074130 (protein product: Dock4-R853H), are associated with dyslexia and/or ASD with reading difficulties." (PMID 32009906, 2019). "Cytokinesis 4 (DOCK4) dedicators involved in dendritic spine development have been identified as risk genes for autism spectrum disorder (ASD), dyslexia, and schizophrenia." (PMID 36882763, 2023). "Given the co-occurrence of the DOCK4 disruption and reading impairment in six of nine people in the family, a panel of 606 unrelated individuals with dyslexia was evaluated." (PMID 23308072, 2012). "Recently, Pagnamenta and colleagues also reported a 594 kbp IMMP2L-DOCK4 deletion resulting in a fusion transcript and an intragenic DOCK4 deletion segregating with dyslexia." (PMID 22102821, 2011). "Another DOCK4 deletion was detected in one case that showed co-segregation with dyslexia within the nuclear family." (PMID 20346443, 2010). "Findings in this study are consistent with the neurodevelopment impairment hypothesis of ASD and dyslexia, in which DOCK4 contributes to a shared genetic factor for both disorders." (PMID 32009906, 2019). "DOCK4 (dedicator for cytokinesis 4), a guanine nucleotide exchange factor (GEF) for the small GTPase Rac1, is one of few genes that are associated with both ASD and dyslexia." (PMID 32009906, 2019). "This led to the identification of a second DOCK4 microdeletion co-segregating with dyslexia." (PMID 20346443, 2010). "DOCK4 is present in the AUTS-1 (7q31.1) region, and previous reports have found that it may be susceptible to multiple neuropsychiatric disorders, such as schizophrenia, dyslexia, and ASDs." (PMID 36882763, 2023). "Together, we identified R853 as a previously uncharacterized site for the regulation of the integrity of Dock4 function, and provides insights in understanding the common molecular pathophysiology of ASD and dyslexia." (PMID 32009906, 2019). "Among them, Dock4 has attracted recent attention as emerging evidence suggests DOCK4 as a candidate gene for several neuropsychiatric diseases, including autism spectrum disorder (ASD), dyslexia and schizophrenia." (PMID 32009906, 2019). "Therefore, investigating the mechanism by which Dock4 and its downstream molecules regulate neuronal function and behavior provides more evidence for understanding the pathogenesis of the co-occurring symptoms of ASD and dyslexia." (PMID 32009906, 2019). "Notably, DOCK4 is one of few shared candidate genes for both ASD and dyslexia." (PMID 32009906, 2019). "There was a deletion of DOCK4 exons 38 to 52 (detected on the 300K array, log Bayes Factor = 44, validated by QMPSF and quantitative PCR) in a single dyslexia case, but no exonic deletions of DOCK4 were detected in 2091 control samples tested on the 550 K SNP array (p = .225, Fisher's exact test)." (PMID 20346443, 2010).
autism spectrum disorder (8 papers, 2019 to 2025). A spectrum of developmental disorders that includes autism, and Asperger syndrome. "Variants in DOCK4 have been associated with response to antidepressants, autism spectrum disorder, and schizophrenia." (PMID 40034430, 2025). "Concurrently, deficiencies in Dock4, coupled with reduced GluN2B expression, have been implicated in eliciting autism-spectrum disorder-like social impairments." (PMID 39282658, 2024). "DOCK4 has been implicated in schizophrenia and autism spectrum disorder." (PMID 34177453, 2021). "(2021) investigated autism spectrum disorder like behavior in conditional Dock4 knockout mice and also observed sex-specific effects." (PMID 38526744, 2024).
liver cancer (7 papers, 2021 to 2024). An epithelial or non-epithelial malignant neoplasm that arises from the liver. "Some studies have demonstrated that EBLN3P promotes the progression of liver cancer via alteration of microRNA-144-3p/DOCK4 pathway, and osteosarcoma through modifying the miR-224-5p/Rab10 signaling axis." (PMID 35517503, 2022). "For example, EBLN3P regulates DOCK4 expression via sponging miR-144-3p competitively, thereby participating in liver cancer's progression." (PMID 36371574, 2022). "The lncRNA EBLN3P, functioning as a competitive sponge of miRNA‐144‐3p, positively modulates DOCK4 in the ceRNA pathway and facilitates adverse processes in liver cancer." (PMID 34890108, 2022). "Then, they performed functional assays, which revealed that forced EBLN3P expression resulted in the promotion of the proliferation and metastasis of liver cancer cells via alteration of miRNA-144-3p/DOCK4 signal." (PMID 34109193, 2021). "It has recently been demonstrated that EBLN3P may act as a ceRNA, regulating the expression of DOCK4 through miR-144-3p sequestration, promoting liver cancer cell proliferation, migration, and invasion." (PMID 34827671, 2021).
schizophrenia (7 papers, 2012 to 2025). A major psychotic disorder characterized by abnormalities in the perception or expression of reality. "A recent study conducted in the Jewish population also identified a SNP (rs2074127) in DOCK4 associated with schizophrenia however, this SNP is not in LD with the DOCK4 SNPs reported in this study." (PMID 22479419, 2012).
melanoma (6 papers, 2017 to 2024). A malignant, usually aggressive tumor composed of atypical, neoplastic melanocytes. "ShcD overexpression sustains amoeboid movement in melanoma cells, by suppressing the Rac1 signaling pathway through the confinement of DOCK4 in the cytoplasm." (PMID 33202906, 2020). "DOCK4-silenced cells recapitulated the elongated morphology of ShcD-silenced cells confirming the ShcD role in melanoma cell invasiveness through DOCK4 regulation." (PMID 33202906, 2020). "RTL1 overexpression activates the Wnt pathway by increasing the levels of DOCK4 and MACF1, both of which enhance the release of β-catenin from the destruction complex and increase the stability of β-catenin in melanoma cells." (PMID 38225934, 2024).
atherosclerosis (5 papers, 2021 to 2025). A disease characterized by the build-up of fatty material and calcium deposition in the arterial wall resulting in partial or complete occlusion of the arterial lumen. "A recent study discovered that human atherosclerosis has higher levels of DOCK4 and scavenger receptor class-B type-1 (SR-B1), and DOCK4 activates Rac1 by boosting LDL binding to SR-B1, promoting SR-B1 internalization and transport of LDL." (PMID 36882763, 2023). "SR-B1 drove LDL transcytosis of the endothelium by DOCK4 to promote atherosclerosis." (PMID 35047576, 2021). "In addition, DOCK4 boosts atherosclerosis via internalization of SR-B1 and transport of LDL." (PMID 33968925, 2021). "Knockdown of DOCK4 suppressed SR-B1–dependent LDL transcytosis in cultured cells, and both Scarb1 and DOCK4 mRNA levels were increased in the atherosclerosis-prone lesser curvature of mouse and human aortic arch." (PMID 40013359, 2025). "Additionally, a recent study reported that DOCK4 promotes the internalization of scavenger receptor class B type 1 and LDL transport by activating the RHO GTPase RAC1, which may promote atherosclerosis in endothelial cells." (PMID 36882763, 2023).
bone metastasis (5 papers, 2019 to 2023). Transfer of a neoplasm from its primary site to bones. "Subsequent research using samples from 689 patients in the AZURE trial found that adjusted Cox regression analysis showed that high DOCK4 expression was associated with a higher risk of bone metastasis occurrence." (PMID 38041134, 2023). "This indicates that the use of zoledronic acid can effectively reduce the risk of bone metastasis in patients with high expression of DOCK4." (PMID 38041134, 2023). "Notably, in this regard, the specific association of high DOCK4 with bone metastasis at any time is lost once metastasis has occurred elsewhere." (PMID 30426503, 2019). "In a parallel analysis of DOCK4 levels within the AZURE trial, patients’ high DOCK4 expression correlated with the risk of bone metastasis (HR 2.13, 95%CI 1.06–4.30, p = 0.034)." (PMID 32751181, 2020). "Clearly, these factors need to be borne in mind in the consideration of DOCK4 as a predictive biomarker for zoledronate response in bone metastasis prevention." (PMID 30426503, 2019).
lung adenocarcinoma (5 papers, 2016 to 2025). A carcinoma that arises from the lung and is characterized by the presence of malignant glandular epithelial cells. "DOCK4 has been previously implicated in M2 tumor-associated macrophage (TAM) polarization and angiogenesis in lung adenocarcinoma, contributing to immune-related tumor functions and poor patient prognosis." (PMID 40529490, 2025). "It is hypothesized that LDHA, GPX3 and DOCK4 are new potential targets for lung adenocarcinoma, which can achieve breakthroughs in prognosis prediction, targeted prevention and treatment of lung adenocarcinoma and provide important guidance for anti-tumor." (PMID 38213730, 2024). "The induction of DOCK4 proved crucial in TGF-B-driven lung adenocarcinoma metastasis." (PMID 37324026, 2023).
osteosarcoma (5 papers, 2011 to 2024). A usually aggressive malignant bone-forming mesenchymal neoplasm, predominantly affecting adolescents and young adults. "Dock4-mediated activation of Rap1 GTPase was shown to promote stability of N-cadherin mediated cell–cell junctions in osteosarcoma cells." (PMID 38802496, 2024). "The DOCK4 functions as a guanine nucleotide exchange factor and is involved in regulation of adherens junctions between cells and in cell migration, could suppresses tumor invasion in osteosarcoma mouse cell lines." (PMID 30286182, 2018). "Distinct from the identification of ABR, PREX1 and DOCK2 in non-cancer cells, DOCK4 identification was initially reported in osteosarcoma cells, in which DOCK4 was deleted during tumor progression." (PMID 34783629, 2021).
Anxiety (4 papers, 2020 to 2024). Intense feelings of nervousness, tension, or panic often arise in response to interpersonal stresses. "Both male and female mice were studied in this study, and the Dock4 deficient mice show sex-dependent differences in anxiety levels and learning and memory." (PMID 32244264, 2020). "The present study provides novel evidence indicating that Dock4 deficiency in mice causes ASD-like behaviors, including social and vocalization deficits, elevated anxiety levels, and cognitive dysfunction." (PMID 31388105, 2021). "Dock4 KO mice displayed abnormalities in social behavior, vocalizations, anxiety levels, and learning and memory, accompanied by reduced hippocampal excitatory synapse number and transmission." (PMID 31388105, 2021). "We found that Dock4 KO mice display impaired social novelty preference, increased vocalizations, elevated anxiety levels, and disrupted spatial and working memory." (PMID 32244264, 2020). "Collectively, these results indicate that Dock4 KO mice manifest all three core domains of ASD symptoms, and display elevated anxiety and impaired object and spatial learning." (PMID 31388105, 2021). "We generated and characterized a line of Dock4 knockout (KO) mice, which intriguingly displayed a series of ASD-like behaviors, including impaired social novelty preference, abnormal isolation-induced pup vocalizations, elevated anxiety, and perturbed object and spatial learning." (PMID 31388105, 2021).
breast tumours (4 papers, 2019 to 2025). "In a tissue microarray analysis from the AZURE trial, individuals with elevated DOCK4 levels in primary breast tumors showed markedly higher rates of bone recurrence than those with reduced DOCK4 expression." (PMID 40426987, 2025). "DOCK4 expression was initially assessed in a local breast tumour array of 345 unselected breast tumours (88% ductal, 9% lobular, 3% other) with patient data available on tumour grade (18% grade 1, 44% grade 2, 38% grade 3), ER and axillary lymph node involvement." (PMID 30426503, 2019).
attention deficit-hyperactivity disorder (3 papers, 2010 to 2024). A disorder characterized by a marked pattern of inattention and/or hyperactivity-impulsivity that is inconsistent with developmental level and clearly interferes with functioning in at least two settings (e.g. at home and at school). "In contrast to recent CNV studies on attention-deficit/hyperactivity disorder, our data therefore suggest that haploinsufficiency of IMMP2L might be benign, with deletions of DOCK4 more likely to be of etiological relevance." (PMID 20346443, 2010).
glioblastoma (3 papers, 2021 to 2025). The most malignant astrocytic tumor (WHO grade IV). "A recent study reported that the overexpression of DOCK4 suppresses the tumorigenicity of glioblastomas (GBM) stem‐like cells, and an increased level of DOCK4 predicts improved patient survival of GBM." (PMID 34432380, 2021).
lung carcinoma (3 papers, 2021 to 2025). "Among the predicted targets, SASH1 and DOCK4, which have been implicated in lung cancer prognosis, are recognized as oncogenes in LUAD." (PMID 40529490, 2025). "Upregulation of DOCK4 was found associated with metastases of breast and lung cancer." (PMID 34804930, 2021). "To date, the roles of ABR, PREX1, DOCK2, and DOCK4 in lung cancer are largely unknown, and the underlying mechanisms remain to be explored." (PMID 34783629, 2021). "The downregulation of ABR, PREX1, DOCK2 and DOCK4 in NSCLC can be induced by promoter methylation, and their methylation profiles might be potential indicators for lung cancer screening." (PMID 34783629, 2021). "Thus, DNA hypermethylation might contribute to the downregulation of ABR, PREX1, DOCK2, and DOCK4 in NSCLC, and the methylation profiles of the four key Rho GEFs may be novel biomarkers for lung cancer screening." (PMID 34783629, 2021).
stomach adenocarcinoma (3 papers, 2021 to 2024). "DOCK4 has been identified to be a biomarker in stomach adenocarcinoma related to immune infiltration, so is in colon adenocarcinoma." (PMID 38443923, 2024). "According to the boxplot analysis, the mRNA levels of DOCK4, GNAS, TGFB1, SELE, and SMARCE1 demonstrated a considerably higher expression in gastric adenocarcinoma than in healthy controls." (PMID 37037466, 2023).
diabetes (2 papers, 2019 to 2021). "However, very little is known with respect to the impact of DOCK4 in diabetes." (PMID 33968925, 2021).
Nephropathy (2 papers, 2024 to 2025). A nonspecific term referring to disease or damage of the kidneys. "USP36 deubiquitinates DOCK4 (a mono-ubiquitinated protein), which promotes Wnt/β catenin signaling, diabetic tubular renal injury, and consequently nephropathy." (PMID 41007744, 2025).
non-small cell lung carcinoma (2 papers, 2007 to 2022). A group of at least three distinct histological types of lung cancer, including non-small cell squamous cell carcinoma, adenocarcinoma, and large cell carcinoma. "While DOCK4 regulates formation of cellular junctions and is disrupted in prostate and ovarian cancers,SPARCL1 acts as a negative regulator of cell proliferation and its down-regulation is detected in prostate, colon, and non-small cell lung carcinomas." (PMID 17559657, 2007).
osteoporosis (2 papers, 2024 to 2025). A condition of reduced bone mass, with decreased cortical thickness and a decrease in the number and size of the trabeculae of cancellous bone (but normal chemical composition), resulting in increased fracture incidence. "This research has identified DOCK4 as a potential diagnostic marker for osteoporosis, regulated by lncRNAs NONHSAT122778.2 and NONHSAT122777.2 and four miRNAs." (PMID 38443923, 2024). "DOCK4 is a potential biomarker for elderly osteoporosis diagnostic." (PMID 38443923, 2024). "Despite the successful identification of DOCK4 as a potential biomarker for osteoporosis (OP) through the integration analysis of lncRNA and mRNA expression data, and the potential regulatory mechanisms involving lncRNAs and miRNAs, the limited sample size in our study is a significant limitation." (PMID 38443923, 2024).
ovarian carcinoma (2 papers, 2007 to 2021). A malignant neoplasm originating from the surface ovarian epithelium. "In conclusion, DOCK4 is potentially associated with immune cell infiltration and represents a valuable prognostic biomarker in ovarian cancer patients." (PMID 33613670, 2021). "We found that DOCK4 upexpression was associated with a worse prognosis in ovarian cancer." (PMID 33613670, 2021). "Given that DOCK4, the promising biomarker for prognosis of ovarian cancer patients, could be detected in blood contributing to clinical treatment, we then investigated the expression pattern of DOCK4 in blood samples consistent with DOCK4 encoding a secreted protein." (PMID 33613670, 2021). "Certainly, further work will be necessary to identify the role of DOCK4 in immune activity regulation in ovarian cancer." (PMID 33613670, 2021). "There were only 4 PPAR-TRGs (AP2A2, DOCK4, HSDL2, and PDK4) out of 269 DEGs, which are associated with platinum chemosensitivity in ovarian cancer." (PMID 33613670, 2021). "This suggests that DOCK4 plays a moderate role in interacting with immune cell infiltration in ovarian cancer." (PMID 33613670, 2021). "The overall survival analysis results of array data and RNA-Seq data from Kaplan-Meier plotter indicated that DOCK4 gene upexpression was a poor prognosis of ovarian cancer patients." (PMID 33613670, 2021). "Furthermore, other experimental methods in vivo and in vitro would be considered to characterize the regulation mechanism of DOCK4 in ovarian cancer." (PMID 33613670, 2021). "Therefore, much more efforts are demanded to reveal the mechanism of DOCK4 targeted by PPARδ in ovarian cancer patients' immune cells, especially neutrophils." (PMID 33613670, 2021). "The function and mechanism of DOCK4 in ovarian cancer need further research." (PMID 33613670, 2021). "In this study, we firstly identified a potential function suggesting the chemotherapy-sensitive role of DOCK4 in ovarian cancer, which might be correlated with immune cell infiltration." (PMID 33613670, 2021). "Altogether, DOCK4 might be a candidate prognosis biomarker for ovarian cancer patients." (PMID 33613670, 2021). "Therefore, the role of DOCK4 in neutrophils remains to be explored in ovarian cancer progression." (PMID 33613670, 2021). "Our results showed that DOCK4 could be detected in the peripheral blood of ovarian cancer patients." (PMID 33613670, 2021). "Therefore, we have reason to believe that DOCK4 might be the potential prognosis biomarker for ovarian cancer." (PMID 33613670, 2021). "We further found that the expression of DOCK4 is correlated with the levels of CD4+ T cell infiltration, dendritic cell infiltration, and neutrophil infiltration in these ovarian cancer patients." (PMID 33613670, 2021).